BRD4 (bromodomain containing 4)
Diseases named in the same sentence as BRD4 in open-access papers (continued):
Sharing a sentence is not in itself a finding about the gene and the disease.
infection (continued). "Restricting transcription of the viral replication proteins may have a rate-limiting impact on viral DNA replication processes at the onset of infection, or Brd4 might promote viral DNA replication in an E2-dependent manner." (PMID 27879331, 2016). "Therefore, to determine the role of Brd4 in HPV18 gene expression at very early stages of infection, subconfluent HFKs were depleted of Brd4 with two different small interfering RNAs (siRNAs) and infected 24 to 48 h later with 100 VGE/cell of HPV18 quasivirus." (PMID 27879331, 2016). "However, this Brd4-enrichment of factors could also be important for replication at early stages of infection, when the E1 and E2 proteins are expressed in very limited quantities." (PMID 34386523, 2021). "Interestingly, we observed that treating A549 cells with 10 μM ZL0454 resulted in a reversal to many RSV-stimulated changes; 95 proteins that had significantly increased abundance on the BRD4 complex following RSV-infection were significantly reduced following ZL0454 treatment." (PMID 33799525, 2021). "Moreover, the upregulation of BRD4 is also found in the uterus and fetal membranes induced by labor and infection, and severe early-onset preeclampsia placenta, which may lead to adverse pregnancy outcomes." (PMID 33462181, 2021). "Thus, Brd4 is an activator of HPV18 gene expression at early times after infection." (PMID 27879331, 2016). "We propose that, while E1, E2 and Brd4 might bind host chromatin at early stages of infection, there is a temporal and functional switch at later stages and increased E1 and E2 levels promote viral DNA amplification, displacement of Brd4 and growth of a replication factory." (PMID 24278023, 2013). "BRD4 depletion increased transcription in both HIVGKO and HIVGKO‐ΔTat infections, consistent with its role in antagonizing Tat-p‐TEFb engagement and recruiting repressive SWI/SNF complexes." (PMID 41414674, 2025). "To further study the proviral effects of epigenetic regulators, we next examined the BRD4 inhibitor JQ1 in our CPE and viral RNA assays during infection of 293TAT cells." (PMID 36305426, 2022). "WT and SMARCA4 complex-depleted cells in the absence or presence of pRSV infection were assayed for SMARCA4, BRD4 and RNA Pol II binding to the proximal MMP9 promoter." (PMID 33732255, 2021). "We identify 101 proteins that are significantly enriched in the BRD4 complex and are responsive to both RSV-infection and BRD4 inhibition." (PMID 33799525, 2021). "The reduction of memory P14+CD8+ T cells upon Brd4 deletion largely results from defective clonal expansion of effector P14+CD8+ T cells, which differentiate into memory cells after the resolution of infection." (PMID 34512660, 2021). "Altogether, our data suggests that the BRD4 complex integrates signals from the NF-κB, AP1, and Wnt pathways during RSV-infection and facilitates crosstalk between them." (PMID 33799525, 2021). "BRD4 is the most well-studied BET protein in response to various stresses, including infection and immune stimulation." (PMID 33462181, 2021). "Three inhibitors against BRD4, JQ-1, OTX-015 and I-BET 151, exhibited viral inhibition upon PRV-GFP infection." (PMID 32208449, 2020). "Inhibition of the bromodomain proteins BRD2/BRD4 by compounds PFI-1 and (+)-JQ1 were found to increase infection." (PMID 28114951, 2017). "We show that, upon infection of primary human keratinocytes with HPV18 quasivirus, Brd4 activates viral transcription and replication." (PMID 27879331, 2016). "In addition, BRD4 was pharmacologically inhibited in vivo using JQ1, and hepatic inflammation and worm load were evaluated at 14 days post-infection." (PMID 40616163, 2025). "The overlapping ratio of BRD4 and MED1 puncta and the DNA-FISH signal of GBP gene family region is significantly increased after infection, suggesting the GBPs gene region tends to relocate into LLPS transcription factory zone to efficiently initiate this immune-defense gene expression." (PMID 36195603, 2022).
infection (continued). "In BRD4-KO cells, exogenously alteringmiR-765 expression, by infection withlv-pre-miR-765 or lv-antagomiR-765, did not change BRD4 expression or cellular functions including proliferation, migration and apoptosis." (PMID 33686960, 2021). "It is known that within the first 8 h of permissive infection with clinical isolates of HCMV, BRD4 along with CycT1 and CDK9 (the RNAPII-activating P-TEFb complex) accumulate at nuclear sites, known as the transcriptosome, where the transcriptionally active HCMV genome resides." (PMID 32714883, 2020). "Regardless, the possibility that BRD4 may be recruiting the activating P-TEFb to the MIEP makes it an attractive target for inhibition, at least during lytic infection." (PMID 32714883, 2020). "Treatment of BRD4 depleted cells with JQ-1, OTX-015 and I-BET 151 showed no cumulative effect on PRV-GFP infection, thus suggesting that BRD4 inhibitors specifically acted on BRD4 to reduce PRV infection." (PMID 32208449, 2020). "To ensure that the depletion of Brd4 did not impact quasiviral infection and entry, we also measured total viral DNA and unreplicated viral DNA at the 72-h point." (PMID 27879331, 2016). "Unexpected, we found transient expression of a plasmid for BRD4 T1186A/T1212A mutant, a mutant with a critical role in anisomycin and heat shock-induced BRD4 release from chromatin-targeting, had little effect against HSV-1 lytic infection, suggesting other mechanisms may exist." (PMID 40812420, 2025). "Notably, in HIVGKO-infected cells, LRAs did not further elevate GFP+ frequency or GFP MFI upon p400 or BRD4 depletion, consistent with near-maximal activation during acute infection and potential cytotoxic limits." (PMID 41414674, 2025). "Further investigation will be required to confirm the exact nature of the BRD4/AP1 interaction, but these results suggest that BRD4 may recruit both AP1 homodimers and AP1 heterodimers via distinct interaction surfaces during RSV-infection." (PMID 33799525, 2021). "The Brd4 protein has been shown to be involved in viral transcription and replication at different phases of the life cycle; however, its role at the onset of viral gene expression immediately after infection has not been studied." (PMID 27879331, 2016). "We conclude that the IRF1 functions in two modes- in absence of infection, ambient IRF1 mediates constitutive expression of the intrinsic IIR, whereas in response to RSV infection, the BRD4 CRC independently activates pSer2 Pol II to mediates robust expression of the intrinsic IIR." (PMID 38601157, 2024).
hematological malignancies (22 papers, 2012 to 2025). "Specifically, BRD4 has been shown to associate with the MYC gene in hematological malignancies and drive MYC expression." (PMID 25537515, 2015). "Previous studies reported that over expression of BRD4 was linked to tumorigenesis and progression in several solid tumors and some hematologic malignancies; however, its role in T-ALL remains unclear." (PMID 33888130, 2021). "The most significantly hypermethylated CpGs were frequently linked to genes involved in the pathogenesis of hematological diseases, including RUNX1, BRD4, SRSF2, SETBP1 and TNFSF10." (PMID 40319310, 2025). "Preclinical and clinical studies have demonstrated the efficacy of BET inhibition in several hematological malignancies 29, 30, in which inhibition of BRD4 leads to downregulation of MYC expression 31, a master regulator of cell survival and proliferation." (PMID 38169595, 2024). "More than 20 BRD4 inhibitors are currently undergoing clinical trials for the treatment of hematological malignancies, solid tumors, and other diseases." (PMID 36224471, 2022). "Our findings provide insight into the regulatory mechanism by which HOXA genes and BRD4 activate lnc-eRNAs in the pathogenesis of aggressive hematologic malignancies." (PMID 33143730, 2020). "Apart from their functions in MK differentiation, RUNX1, GATA1 and c-MPL as well as other epigenetic factors such as BRD4 found in this study are dysregulated in a broad spectrum of hematological malignancies as well as solid tumors." (PMID 26575292, 2015). "Together, these data suggest that CD180 mRNA levels may be a relevant pharmacodynamic biomarker for BRD4 inhibitors in hematological malignancies." (PMID 37460961, 2023). "For instance, the BRD4‐targeting PROTACs, such as dBET1 and ARV‐825, selectively deplete BRD4 and MYC‐driven transcription in hematologic malignancies." (PMID 41362117, 2025). "Furthermore, another BRD4 inhibitor similar in structure to JQ1, OTX015, is currently being used in phase I clinical trials for hematological malignancies." (PMID 25537515, 2015). "Given the fact that BET inhibitors have clear anticancer activity in a variety of solid tumors and hematologic malignancies, our findings provide evidence and a rationale for the development of novel therapeutic strategies to improve immune responses in AML based on targeting BRD4." (PMID 35918330, 2022). "Since bromodomain and extraterminal (BET) proteins (such as BRD2 and BRD4) regulate MYC‐dependent transcription, various potent and selective small‐molecule inhibitors of these proteins have been developed and clinical trials are currently ongoing in hematological malignancies." (PMID 32623836, 2020). "Additionally, we did not observe any change in the expression of MCL1 (data not shown), another validated BRD4 target in hematological malignancies." (PMID 25537515, 2015).
cardiovascular diseases (13 papers, 2016 to 2025). "Several BET inhibitors, including JQ1, are currently undergoing clinical evaluation in oncology, and recent studies suggest a potential role for BRD4 in cardiovascular diseases." (PMID 41226402, 2025). "Most of these studies have revealed that BRD4 is a key regulator contributing to the development of cardiovascular diseases." (PMID 35694272, 2022). "Especially, a key role of BRD4 in cardiovascular diseases has recently been extensively investigated." (PMID 32392533, 2020). "Considering the existent structural and functional differences between BRD2 and BRD4, it raises our interests to explore the role of BRD2 in cardiovascular diseases." (PMID 35694272, 2022). "Bromodomain containing protein 4 (BRD4) is a reader of epigenetic marks and a key target in oncology, inflammation and cardiovascular disease with several inhibitors currently in clinical trials." (PMID 27128490, 2016). "For example, a BD-independent interaction between BRD4 and GATA4 has recently been reported to regulate the mitochondrial homeostasis in the adult heart, and the interaction interface is a potential target for pharmacological treatment of cardiovascular diseases." (PMID 40149571, 2025).
heart disease (9 papers, 2018 to 2024). "Following gene-body p300 modification, a transcriptional elongation activator, Brd4, associates with acetylated histones and plays a role in stress-related heart disease." (PMID 29747586, 2018). "Numerous researchers have investigated the therapeutic benefits and mechanisms of action of BRD4 inhibitors in heart disease because BRD4 functions in controlling gene expression in heart disease." (PMID 39215370, 2024). "Blockade of the bromodomain protein Brd4 by small molecule compounds inhibited pathological gene expression and progression of heart disease in a mouse model of cardiac pressure overload and in CMs in vitro." (PMID 29374152, 2018). "BRD4 has gradually been recognised as a target for epigenetic regulation in heart disease." (PMID 37528096, 2023).
liver (7 papers, 2018 to 2025). "More importantly, enhancer inhibitors (JQ1 and I-BET-762) or BRD4 knockdown attenuated CCT3 expression in gastrointestinal tumor cells." (PMID 36313331, 2022). "BRD4 plays an important regulatory role in digestive system tumors." (PMID 35252219, 2021). "Indeed, in CCl4-mediated chronic liver injury, TNFα in LSECs leads to the interaction of NF-κB with histone acetyltransferase protein 300 (p300) and bromodomain containing 4 (BRD4) to epigenetically upregulate CXCL1 and CCL2, which significantly increases liver inflammation and promotes fibrosis." (PMID 40595432, 2025).
renal diseases (7 papers, 2016 to 2025). "In line with our findings in the kidney after UUO injury, Brd4 expression also increased in human kidneys with renal diseases." (PMID 27732564, 2016). "The impact of BRD4 in tumorigenesis and development of renal disease may illustrate an overlapping role in RCC formation in CKD." (PMID 40510153, 2025). "Thus, BRD4 inhibition could be useful for curbing the maladaptive UPR activation mechanisms, thereby ameliorating the progression of renal disease." (PMID 38481808, 2024).
metabolic disease (6 papers, 2017 to 2022). A congenital disorder (due to inherited enzyme abnormality) or acquired (due to failure of a metabolically important organ) disorder resulting from an abnormal metabolic process. "For example, inhibition of Brd4 has been shown to reduce systemic inflammation and abrogate inflammation-related metabolic diseases, including atherosclerosis and liver fibrosis." (PMID 33830083, 2021). "Therefore, by regulating autophagy BRD4 ameliorates the effects of metabolic disorders on the ECM." (PMID 35308165, 2022).
adenocarcinoma (5 papers, 2016 to 2025). A common cancer characterized by the presence of malignant glandular cells. "In prostate adenocarcinomas, BRD4 associates with AR and is recruited to AR target genes, thus activating AR signaling pathways for growth and survival of adenocarcinoma cells." (PMID 40370549, 2025). "Our findings that BRD4 in NEPC primarily controls the LP drivers and gene programs are in stark contrast to the fact that in CRPC adenocarcinomas BRD4 controls primarily AR signaling." (PMID 40370549, 2025). "In this regard, the co-inhibition of FAK and BRD4 may lead to impaired activation of dynamics of T regulatory cell populations and IL8-linked NF-KB network in NSCLC adenocarcinomas, including those with KRAS mutations." (PMID 32793596, 2020). "In line with the crucial role of BRD4, its expression is significantly higher in both t-NEPC and de novo NEPC subtypes, compared to adenocarcinomas." (PMID 40370549, 2025). "While our study focuses on the effect on the adenocarcinoma subtype of NSCLC, the co-inhibition of FAK and BRD4 may be effective for the squamous subtype of NSCLC as well." (PMID 32793596, 2020). "Chromatin immunoprecipitation assays in tumors showed that BRD4 is recruited at the IL6 promoter and that (+)-JQ1 treatment impairs BRD4 occupancy, suggesting that (+)-JQ1 plays a primary role in hindering IL6 expression in C26 adenocarcinoma tumors." (PMID 29167426, 2017).
hematological cancer (5 papers, 2013 to 2025). "When a range of hematological cancer cell lines, including ALL, MM, and DLBCL types, were treated with AZD5153, a novel BRD4 inhibitor, all demonstrated considerable reduction in CD180 mRNA levels." (PMID 37460961, 2023). "BRD4 activates and keeps the MYC expression constant in hematopoietic cancers." (PMID 35401196, 2022).
immune diseases (5 papers, 2021 to 2024). "Our unpublished results also have revealed that selective targeting of BRD4-BD2 inhibits Th2 cell differentiation, thereby paving the way for the applications of BRD4 BD1- vs. BD2-selective inhibitors to selectively target Th17- or Th2-related immune diseases." (PMID 34540900, 2021).
neurodegenerative disease (5 papers, 2024 to 2025). A disorder of the central nervous system characterized by gradual and progressive loss of neural tissue and neurologic function. "This radiotracer offers potential advancement in the diagnosis and research of neurodegenerative diseases and related disorders involving BRD4 dysregulation." (PMID 39770515, 2024). "Overall, the roles of HMGB1, BRD4 and SOX11 as key regulators in the GRN for contrasting DEGs suggests these genes may be key drivers of associated differential alterations in neuroinflammatory, epigenetic and adult neurogenesis-related processes in neurodegenerative diseases." (PMID 41318503, 2025). "The neuroprotective effects of JQ1 in our study further support the notion that targeting Brd4 and other BET proteins can mitigate the neurotoxic effects of activated microglia in neurodegenerative diseases." (PMID 40305227, 2025).
inflammation (4 papers, 2020 to 2022). Aberrant reaction of the microcirculation characterized by movement of fluid and leukocytes from the blood into extravascular tissues. "Therefore, in this study, the role of BRD4 was investigated in a model system of endothelial inflammation to better understand whether pharmacological BRD4 inhibition with apabetalone and JQ1 might be sufficient to prevent endothelial monolayer disturbance during the inflammatory response." (PMID 36364277, 2022).
neurological disorders (4 papers, 2020 to 2025). "Among these various interacting genes, four (RAF1, BRD4, ATRX, and TKT) have been associated with syndromic congenital conditions involving craniofacial abnormalities, heart defects, and neurological disorders." (PMID 40525707, 2025).
blood cancer (3 papers, 2021 to 2025). "AZD5153, in clinical development, binds simultaneously to both bromodomains of BRD4 and has been confirmed to regulate MYC and HEXIM1 transcription, indicating its efficacy as an oral BET/BRD4 inhibitor for blood cancer." (PMID 40430531, 2025).
bone disorder (2 papers, 2019 to 2020). "This study offers an emerging BRD4-mediated epigenetic pathway, which determines mesenchymal stem cell fate in glucocorticoid-induced osteoporotic skeleton and fatty marrow, and highlights the perspective of BRD4 inhibitor protection against glucocorticoid overmedication-mediated bone disorders." (PMID 32575577, 2020). "Here we further presented that I-BET151 harbored the inhibitory effect on inflammatory cytokine secretion and osteoclast formation in MM, altogether demonstrating that the inhibition of BRD4 could be a promising strategy for the treatment of lytic bone disorders." (PMID 30455393, 2019).
CNS tumor (2 papers, 2023 to 2024). "As only a few CNS tumors with BRD4::LEUTX fusions have been described, we herein characterize a cohort of 9 such cases (4 new, 5 previously published) to further describe their clinicopathologic and molecular features." (PMID 38500181, 2024).
infectious disease (2 papers, 2023 to 2025). A disorder directly resulting from the presence and activity of a microbial, viral, or parasitic agent in humans. "I-BET-762 (molibresib) had been widely studied as a BRD4 Inhibitor for its therapeutic potential in various malignancies, while TPCA-1 had been extensively used in infectious diseases for its anti-inflammatory effect." (PMID 40529377, 2025).
neurodevelopmental disorder (2 papers, 2022). A behavioral and cognitive disorder with onset during the developmental period that involves impaired or aberrant development of intellectual, motor, or social functions. "Several factors involved in the recruitment of P-TEFb to paused RNApol2 have been implicated in neurodevelopmental disorders with a CdLS-like phenotype, including BRD4." (PMID 35615272, 2022).